FADS2B (fatty acid desaturase 2B (pseudogene))
Synonyms: FADS2BP; formerly FADS2P1
Gene: Transcribed unprocessed pseudogene on chromosome 11 (56,890,613 to 56,927,885, forward strand). Ensembl gene ENSG00000274150.
Subcellular location: Endoplasmic reticulum membrane